SIRT1 (sirtuin 1)
Diseases named in the same sentence as SIRT1 in open-access papers (continued):
Sharing a sentence is not in itself a finding about the gene and the disease.
muscular dystrophies (8 papers, 2014 to 2024). "Resveratrol, an activator of SIRT1, ameliorates muscular function in muscular dystrophy patients and dystrophin-deficient mdx mice, although its mechanism is still not fully elucidated." (PMID 36097021, 2022). "Although further research is needed to clarify the molecular mechanisms underlying the protective role of SIRT1 in DMD, we propose SIRT1 as a novel hypothetical therapeutic target for patients with muscular dystrophies." (PMID 34205021, 2021). "Therefore, SIRT1 activation may counteract the fragility of the membranes associated with muscular dystrophies." (PMID 36097021, 2022). "Thus, the antifibrotic effect associated with SIRT1 activation may be advantageous in treating muscular dystrophies." (PMID 27073590, 2016). "Resveratrol, an activator of the protein deacetylase SIRT1 and an antioxidant, decreases muscular and cardiac oxidative damage and improves pathophysiological conditions in animal models of muscular dystrophy (MD)." (PMID 38797976, 2024). "SIRT1-MKO mice showed muscular pathology similar to mild muscular dystrophies with increased numbers of centrally nucleated small myofibers and decreased numbers of middle-sized (2000–3001 μm2) myofibers compared to those of wild-type (WT) mice." (PMID 31242212, 2019). "Although further research is needed to clarify the molecular mechanisms underlying the protective role of SIRT1 in mdx mice, we propose SIRT1 as a novel therapeutic target for patients with muscular dystrophies." (PMID 27073590, 2016). "In this review, we will highlight the roles of SIRT1 in the muscle especially focusing on recent evidence showing the therapeutic potential against muscular dystrophies." (PMID 27073590, 2016). "We also discuss molecular mechanisms by which SIRT1 activation ameliorates muscle pathology in muscular dystrophies." (PMID 27073590, 2016). "Taken together, these findings suggest that targeting oxidative stress will be an effective strategy for treating muscular dystrophies and that SIRT1 activation protects muscles of mdx mice, at least in part, by suppressing oxidative stress." (PMID 27073590, 2016). "These beneficial effects appear to be attributed to the activation of SIRT1 with consequent fiber shift from fast-to-slow twitch, which prevents muscular dystrophies.The optimal dose of resveratrol treatment in most of the experiments is shown to be 100 mg/kg/day." (PMID 34205021, 2021). "Further studies of SIRT1 activation will reveal its effect on muscular dystrophies." (PMID 31242212, 2019). "In addition, previous studies suggested that targeting SIRT1 as a key regulator of energy might improve the muscle pathology in patients with muscular dystrophies." (PMID 29887910, 2018). "Therefore, further research is needed to clarify the anti-inflammatory effect of SIRT1 in the dystrophic muscle, and a study using SIRT1 transgenic mice may provide its efficacy in the muscle inflammation in muscular dystrophy." (PMID 27073590, 2016). "PGC-1α, a bona-fide target of SIRT1, stimulates the neuromuscular gene program (NMJ), as a coactivator of GABP transcription factor, and counteracts the abnormalities of NMJ morphology in a muscular dystrophy model." (PMID 25032964, 2014). "Considering that increasing SIRT1 activity decreased the MND volume (i.e., increased the number of nuclei), it will be of interest in future studies to investigate SIRT1 as a therapeutic target, for diseases where nuclear alteration is part of the pathophysiology, such as in muscular dystrophies." (PMID 29574748, 2018). "Our observations that SIRT1 transgenic muscle consists of higher percentage of slow-twitch oxidative myofibers and express high levels of utrophin and NMJ genes prompted us to test whether SIRT1 overexpression protects from muscular dystrophy." (PMID 25032964, 2014).
thrombosis (8 papers, 2018 to 2023). "Recently, the role of SIRT1 in the mechanism of the increased incidence of deep venous thrombosis (DVT) associated with aging was also investigated recently." (PMID 38304233, 2023). "The intravenous injection of EPCs treated with Resveratrol (a SIRT1 agonist) promotes thrombus resolution in a murine model of venous thrombosis in vivo." (PMID 36639616, 2023). "The data presented herein are related to the research article entitled “Danhong Huayu Koufuye prevents venous thrombosis through antiinflammation via Sirtuin 1/NF-κB signaling pathway”." (PMID 31528671, 2019). "Moreover, SIRT1/FOXO1 signaling pathway has been identified as a promising target to prevent VWF-mediated arterial thrombosis." (PMID 37415610, 2023). "SIRT1/FoxO1 could be a promising target for preventing AS and arterial thrombosis." (PMID 35607519, 2022). "RE enhanced VEGF and SIRT1 expression levels and increased the MVD in the thrombosis area." (PMID 36639616, 2023). "Obtained data revealed that chronic exposure to IS promotes arterial thrombosis via increased levels of complex tissue factor/factor VII, plasminogen activator inhibitor-1 (PAI-1), platelet activation, as well as decreased aortic levels of SIRT1 and SIRT3." (PMID 30546314, 2018). "However, sub-chronic stress did not modify the expression of Sirt1, a modulator of TF expression and of arterial thrombosis, as previously shown in BDNFMet/Met mice, in all experimental groups considered." (PMID 30347685, 2018). "However, whether exercise can upregulate SIRT1 expression in deep vein thrombosis has not been reported." (PMID 36639616, 2023).
vascular dementia (8 papers, 2019 to 2026). A degenerative vascular disorder affecting the brain. "Collectively, the prevalence of elevated levels of circulating TMAO impaired cognitive function in vascular dementia rats through the downregulation of SIRT1." (PMID 36429082, 2022). "Antioxidants and SIRT1 activators may decrease the progression of vascular dementia by repairing the oxidative damage." (PMID 41032496, 2025). "This investigation employed a rat model for bilateral common carotid artery occlusion in order to probe TMAO’s influence on vascular dementia and to determine whether this effect was mediated via regulating the expression of SIRT1." (PMID 36429082, 2022). "GAS targeting SIRT1/BDNF pathway may be a potential therapeutic target for vascular dementia." (PMID 35463081, 2022).
vitiligo (8 papers, 2014 to 2025). Generalized well circumscribed patches of leukoderma that are generally distributed over symmetric body locations and is due to autoimmune destruction of melanocytes. "To further investigate the molecular pathways underlying the protective role of SIRT1 activation seen in keratinocytes from perilesional vitiligo skin, we analysed caspase-3 activity in the presence of specific MAPK inhibitors." (PMID 24410795, 2014). "This was associated with deacetylation of Akt, suggesting that SIRT1-mediated deacetylation and activation of Akt protects perilesional vitiligo keratinocytes from cell death." (PMID 24410795, 2014). "Furthermore, SIRT1 was implicated in the pathogenesis of vitiligo and contributes to skin cell damage via regulating several downstream signaling pathways." (PMID 35625530, 2022). "Acute ER stress is causative of apoptotic death in vitiligo, a process that seems to be facilitated in vitiligo melanocytes due to the low level of NAD-dependent protein deacetylase sirtuin-1 (Sirt1) expression." (PMID 41007740, 2025). "The 3D‐Exos harboring miR‐132‐3p and miR‐125b‐5p can induce Treg cells differentiation and suppress oxidative stress‐induced melanocyte apoptosis by targeting Sirt1 and Bak1 respectively, ultimately alleviating the progression of vitiligo." (PMID 38887870, 2024). "The protective role of SIRT1 activation against inflammation and oxidative stress were also confirmed in keratinocytes from vitiligo patients." (PMID 38304233, 2023). "We therefore propose SIRT1 activation as a novel way of protecting perilesional vitiligo keratinocytes from damage." (PMID 24410795, 2014). "Here, for the first time, we shed light on a new SIRT1 signalling, which suggests a protective role in vitiligo keratinocytes." (PMID 24410795, 2014). "Lesional cells showed only a mild decrease in SIRT1 activity respect to healthy skin from vitiligo patients (NS versus healthy skin)." (PMID 24410795, 2014). "Compared to keratinocytes from healthy and lesional vitiligo skin, perilesional cells exhibited a marked decrease (−37% versus healthy skin, P < 0.001) in SIRT1 activity." (PMID 24410795, 2014). "Hence, our results suggest that, in the presence of Resv, perilesional vitiligo keratinocytes are protected from cellular stress and concurrently show the activation of SIRT1." (PMID 24410795, 2014). "Treating keratinocytes from perilesional vitiligo skin with both Resv and a SIRT-1 inhibitor did not cause any significant change compared to untreated cells." (PMID 24410795, 2014). "In untreated keratinocytes from perilesional vitiligo skin and in keratinocytes from perilesional vitiligo skin after 48 hrs treatment of SIRT1 siRNA 100 nM, SIRT1 protein expression was determined by Western blot analysis to demonstrate the effective knockdown of SIRT-1." (PMID 24410795, 2014). "miR-211 is one of those miRNAs recently shown to be downregulated in lesioned epidermis samples from vitiligo patients in relation with increased expression of a lncRNA, MALAT1, which sequesters miR-211, enhancing SIRT1 expression." (PMID 35883477, 2022). "For the first time, a new SIRT1/Akt, also known as Protein Kinase B (PKB)/mitogen-activated protein kinase (MAPK) signalling has been revealed in vitiligo." (PMID 24410795, 2014). "SIRT1 regulates MAPK pathway via Akt-apoptosis signal-regulating kinase-1 and down-regulates pro-apoptotic molecules, leading to decreased oxidative stress and apoptotic cell death in perilesional vitiligo keratinocytes." (PMID 24410795, 2014). "SIRT1 regulates MAPK signalling via Akt-ASK1 and down-regulates pro-apoptotic molecules, leading to decreased oxidative stress/apoptotic cell death in perilesional vitiligo keratinocytes." (PMID 24410795, 2014). "Here, biopsies were taken from the perilesional skin of 16 patients suffering from non-segmental vitiligo and SIRT1 signalling was investigated in these cells." (PMID 24410795, 2014).
vitiligo (continued). "Among the mechanisms that have been evoked in the modulation of cell stress response, the role of SIRT1 has been recently suggested but its signalling and its possible involvement in vitiligo have never been explored." (PMID 24410795, 2014). "We found that, in perilesional vitiligo cells, the p-ERK level was restored by Resv treatment and caspase-3 activity increased in the presence of ERK inhibitor, although this was reversed by SIRT1 activation, suggesting that SIRT1 protects against apoptosis." (PMID 24410795, 2014). "Another important result of this study is the relationship between SIRT1 activation and MAPK signalling, an up-regulated pathway in response to increased ROS production, which has been yet shown to be markedly affected also in keratinocytes from perilesional vitiligo skin." (PMID 24410795, 2014).
anemia (7 papers, 2008 to 2025). A reduction in the number of red blood cells, the amount of hemoglobin, and/or the volume of packed red blood cells. "There were few studies on the role of SIRT1 in iron metabolism related anaemia of chronic disease or anaemia of inflammation that decreases plasma iron with suppression of erythropoiesis." (PMID 38706642, 2023). "Apart from anemia and leukocytosis among older animals, Sirt1 deletion affected neither frequency of hematopoietic stem cell (HSC) populations in BM nor production of mature blood cells, so they concluded that Sirt1 is not essential for stem cells maintenance and maturation." (PMID 32373350, 2020).
Arrhythmia (7 papers, 2020 to 2025). Any cardiac rhythm other than the normal sinus rhythm. "This study demonstrated that the deficiency of cardiac Sirt1 alters the regulation of Ca2+ and Na+ in cardiomyocytes and stimulates arrhythmia." (PMID 32342656, 2020). "A deficiency in SIRT1 may impair the regulation of intracellular Ca2+ in cardiomyocytes, potentially leading to arrhythmias." (PMID 39636756, 2025). "The aim of the present study was to assess whether Sirt1 deficiency in the heart of mice alters intracellular Ca2+ and Na+ regulation, resulting in cardiac dysfunction and predisposition to arrhythmia." (PMID 32342656, 2020). "Therefore targeting interventions of these pathways, suchas EZH2 inhibitors, Sirt1 activators, and Nedd4-2 modulators, will be the subjectof future studies in an attempt to develop new therapeutic strategies for thetreatment of arrhythmias in clinical practice." (PMID 40630435, 2025).
bipolar disorder (7 papers, 2015 to 2025). A disorder of the brain that causes unusual shifts in mood, energy, activity levels and the ability to carry out day-to-day tasks. "Additionally, SIRT1 activation has been shown to influence mitochondrial function and oxidative stress, which are implicated in the pathophysiology of bipolar disorder." (PMID 39404407, 2024). "In comparison with bipolar depression and healthy controls, BD patients with manic episodes have shown increased levels of NFκβ and SIRT-1." (PMID 39766398, 2024). "SIRT-1 levels are decreased in bipolar depression compared to euthymia, and TNF-α levels seem to be lower in depression than in mania." (PMID 39766398, 2024). "SIRT1 has been suggested to play a role in mood regulation and energy homeostasis, which are crucial in bipolar disorder." (PMID 39404407, 2024). "A total of 5 SNPs belonging to the CACNA1C, GRID1, and SIRT1 genotypes were significantly correlated with bipolar disorder (P < .001), with the majority belonging to the CACNA1C." (PMID 38012695, 2023). "Five SNPs were associated with bipolar disorder, namely rs541349080, rs7295590, and rs7979389 of the CACNA1C genotype; rs145322445 of the GRID1 genotype; and rs35648458 of the SIRT1 genotype." (PMID 38012695, 2023). "Five SNPs were identified as associated with bipolar disorder and belonged to the CACNA1C, GRID1, and SIRT1 genotypes, with the majority belonging to the CACNA1C genotype." (PMID 38012695, 2023). "Accordingly, the CACNA1C, GRID1, and SIRT1 genotypes were identified as carrying the highest risks of bipolar disorder." (PMID 38012695, 2023). "Increased levels of NFκβ and SIRT-1 have been found in mania compared to bipolar depression and healthy controls." (PMID 34295268, 2021). "The journal retracts the article “Activating SIRT-1 Signalling with the Mitochondrial-CoQ10 Activator Solanesol Improves Neurobehavioral and Neurochemical Defects in Ouabain-Induced Experimental Model of Bipolar Disorder” cited above." (PMID 41305017, 2025).
Brain atrophy (7 papers, 2013 to 2023). Partial or complete wasting (loss) of brain tissue that was once present. "In this context, SIRT1 ablation exacerbates neurodegeneration, whereas SIRT1 overexpression improves motor functions and rescued brain atrophy." (PMID 36816109, 2023). "In mouse models of HD, ablation of SIRT1 exacerbates neurodegeneration, whereas SIRT1 overexpression improves motor functions and brain atrophy." (PMID 24093018, 2013). "The activator of SIRT1, SRT2104 was found to attenuate brain atrophy, improved motor movement, and increased cell survival in the N171–82Q HD mice." (PMID 33597872, 2020). "A study proved that AK7 was more specific to SIRT2 compared to SIRT1 and SIRT3 and was found to improved neuronal survival, motor function, reduced brain atrophy, and the levels of aggregated mutant HTT in two genetic mouse models of HD." (PMID 33597872, 2020). "On the one hand, over expression of SIRT1 has been shown to reduce mutant HTT-induced toxicity in HD mouse models, improving motor function and reducing brain atrophy." (PMID 26815359, 2016). "Increased expression of Sirt1 attenuated neurodegeneration and improved motor function in N171-82Q and BACHD mice and attenuated brain atrophy and reduced mutant HTT aggregation in R6/2 mice without prolonging lifespan." (PMID 26815359, 2016).
cyst (7 papers, 2015 to 2025). A sac-like closed membranous structure that may be empty or contain fluid or amorphous material. "Studies show that SIRT1 inhibition—either through silencing or pharmacological means—reduces cyst formation in mice." (PMID 40218970, 2025). "Sirt1, a member of the Sirtuin pathway, has been implicated in ADPKD, as double knockouts of Sirt1 and Pkd1 resulted in prevention of cyst formation." (PMID 37256068, 2023). "Myeloid-specific Sirt1−/− mice exhibited an increased cyst burden in brain tissue compared to wild-type mice following infection with the avirulent ME49 strain." (PMID 36362370, 2022). "The SIRT1 activator resveratrol treatment increased cyst formation, and FK866, an NAD synthetic enzyme Nampt inhibitor, decreased cyst formation in the cystogenic assay of MDCK cells." (PMID 36120538, 2022). "Inhibition of SIRT1 with a pan-sirtuin inhibitor nicotinamide and a specific inhibitor EX-527 slowed cyst growth in three PKD mouse models (embryonic model Pkd1−/−, Pkd1flox/flox:Ksp-Cre, and hypomorphic Pkd1nl/nl)." (PMID 36120538, 2022). "This study elucidates a functional role of SIRT1 in regulating ADPKD and provides a molecular basis for using SIRT1 inhibitors to interfere with cyst formation." (PMID 25972812, 2015). "Additionally, the Class III HDAC SIRT1, was also upregulated in Pkd1 mutant mouse cells and kidneys to promote cyst growth and treatment with the SIRT1-specific inhibitor, EX-527, reduced cyst growth in Pkd1 mouse models." (PMID 35847973, 2022). "Conditional double knockout of SIRT1 and Pkd1 delayed cyst growth in Pkd1flox/flox:Ksp-Cre mice." (PMID 36120538, 2022).